HACD3 (3-hydroxyacyl-CoA dehydratase 3)
Description:
Catalyzes the third of the four reactions of the long-chain fatty acids elongation cycle. This endoplasmic reticulum-bound enzymatic process, allows the addition of two carbons to the chain of long- and very long-chain fatty acids/VLCFAs per cycle. This enzyme catalyzes the dehydration of the 3-hydroxyacyl-CoA intermediate into trans-2,3-enoyl-CoA, within each cycle of fatty acid elongation. Thereby, it participates in the production of VLCFAs of different chain lengths that are involved in multiple biological processes as precursors of membrane lipids and lipid mediators. May be involved in Rac1-signaling pathways leading to the modulation of gene expression. Promotes insulin receptor/INSR autophosphorylation and is involved in INSR internalization.
Synonyms: B-ind1; BIND1; PTPLAD1; HSPC121
Tractability: Antibody: UniProt predicts a signal peptide or a membrane-spanning region. PROTAC: ubiquitination databases record sites on it; its protein half-life has been measured.
Target class: Enzyme; Lyase
Gene: Protein-coding gene on chromosome 15 (65,530,418 to 65,578,349, forward strand). Ensembl gene ENSG00000074696.
Subcellular location: Endoplasmic reticulum membrane
Subcellular location (Human Protein Atlas): Endoplasmic reticulum
Pathways (Reactome):
Metabolism: Synthesis of very long-chain fatty acyl-CoAs
Gene Ontology:
Molecular function: enzyme binding; protein binding; very-long-chain (3R)-3-hydroxyacyl-CoA dehydratase activity; GTPase activator activity; (2E)-enoyl-CoA hydratase activity
Biological process: fatty acid elongation; positive regulation by virus of viral protein levels in host cell; positive regulation of viral genome replication; very long-chain fatty acid biosynthetic process; canonical NF-kappaB signal transduction; Rac protein signal transduction; small GTPase-mediated signal transduction; sphingolipid biosynthetic process; fatty acid biosynthetic process; negative regulation of intracellular signal transduction
Cellular component: endoplasmic reticulum; endoplasmic reticulum membrane; focal adhesion
Genetic constraint (gnomAD): Loss-of-function variants: 26 observed, 42.59 expected, observed/expected ratio (o/e) 0.61, 90% interval 0.45 to 0.85. The upper end of that interval is the gene's LOEUF score, 0.85, which puts it in group 3 of 6, group 1 being the genes least tolerant of losing a copy. Missense variants: 310 observed, 362.89 expected, observed/expected ratio (o/e) 0.85, 90% interval 0.78 to 0.94. Synonymous variants: 120 observed, 131.79 expected, observed/expected ratio (o/e) 0.91, 90% interval 0.78 to 1.06.
Homologues: Orthologues: chimpanzee HACD3 (100% identical), macaque HACD3 (99% identical), rabbit HACD3 (95% identical), dog HACD3 (94% identical), pig HACD3 (94% identical), guinea pig HACD3 (94% identical), rat Hacd3 (91% identical), mouse Hacd3 (91% identical), tropical clawed frog hacd3 (67% identical), zebrafish hacd3 (67% identical), Drosophila melanogaster Hacd2 (35% identical), Caenorhabditis elegans R10E4.9 (14% identical). Paralogues in human: HACD4 (26% identical), HACD2 (19% identical), HACD1 (17% identical).
Diseases named in the same sentence as HACD3 in open-access papers:
HACD3 is named in the same sentence as 10 diseases in open-access papers, as found by Europe PMC text mining. Sharing a sentence is not in itself a finding about the gene and the disease. The quoted sentences say what the papers report.
breast carcinoma (2 papers, 2019 to 2022). "Meanwhile, several other risk model genes were identified in this study (ST6GALNAC4, PLPP2, ELOVL1, HACD1, VAPB, CERS2, ALDH3B2, and HACD3) have not yet been explored in depth in breast cancer." (PMID 36059802, 2022).
glioblastoma (1 paper, 2020). The most malignant astrocytic tumor (WHO grade IV). "Third, IL18 upregulated genes consistent with an effector phenotype that supports growth and proliferation, such as genes related to fatty acid biosynthesis (Dgat2, Scd2, Hacd3) and Hif1a, which promotes glycolysis as well as migration of Tregs in glioblastoma." (PMID 32687059, 2020).
Obesity (1 paper, 2024). Accumulation of substantial excess body fat. "The candidate genes MIF, MAP2K3, HACD3, and MEGF11 excavated in this study are related to obesity and fat deposition." (PMID 39330807, 2024).
HACD3 also shares sentences with these, for which no sentence is quoted: cancer (2 papers); tumor (2); Alzheimer disease (1); colorectal cancer (1); Huntington disease (1); Parkinson disease (1); type 2 diabetes (1).